MGMT (O-6-methylguanine-DNA methyltransferase)
Diseases named in the same sentence as MGMT in open-access papers (continued):
Sharing a sentence is not in itself a finding about the gene and the disease.
glioma (continued). "All these results were independent of MGMT as the glioma lines tested were negative for MGMT as well as the TCGA recurrent samples." (PMID 24287492, 2013). "There are not many studies reporting MGMT promoter methylation frequencies in large series of low-grade gliomas." (PMID 22390413, 2012). "In gliomas, LINE-1 methylation, a global DNA methylation marker, is proportional to MGMT promoter methylation and higher LINE-1 methylation is a favorable prognostic factor in primary GBMs, even compared to MGMT promoter methylation." (PMID 22216282, 2011). "While some studies have demonstrated an increase in MGMT immunostaining or a lower frequency of MGMT promoter methylation in recurrent gliomas after chemotherapy, other authors have not observed any change." (PMID 21269507, 2011). "Many methods and protocols have been applied for MGMT analysis in gliomas, but to date there is no consensus on which strategy should be primarily employed." (PMID 21269507, 2011). "Studies with human glioma tumour samples often revealed a lack of correlation between MGMT protein expression and MGMT promoter methylation status." (PMID 20517307, 2010). "As the treatment with 5-aza-dC/VPA slightly increased mRNA levels of MGMT in cultured glioma cells (including U87MG, U251MG and transformed NHA cells), methylation status might be involved in MGMT regulation to some extent." (PMID 17547775, 2007). "With respect to temozolomide response, expression of the repair enzyme MGMT was suggested as the major resistance factor and lack of MGMT expression in gliomas is mainly based on gene promoter methylation." (PMID 17342095, 2007). "However, even for gliomas with methylated MGMT promoters, a large number of patients are still non-responding to TMZ treatment, indicating that a high MGMT level cannot cover all mechanism for the TMZ responsiveness." (PMID 39865088, 2025). "Unlike contrast agents for MRIs, which rely on blood-brain barrier disruption and may be influenced by tumor microenvironment changes, FET uptake is mediated through the LAT1 transporter and reflects active glioma metabolism, regardless of MGMT status." (PMID 40994524, 2025). "As GScore increases, glioma patients tend to have higher WHO grades and shorter overall survival (OS) and are more likely to exhibit isocitrate dehydrogenase (IDH) wildtype status and MGMT promoter unmethylation, which all indicate that elevated GScore is associated with poor clinical outcomes." (PMID 39754188, 2025). "Irrespective of IDH status, an indication of the MGMT status as assessed by APTw MRI is of clear value for preoperative planning and the determination of the surgical strategy in a contrast-enhancing suspected glioma." (PMID 40560010, 2025). "In particular, this research group described how this miRNA is able to regulate MGMT at the post-transcriptional level, and, only in cell lines, they observed that the expression by transfection of miR-648 enhanced the responsivity of TMZ in MGMT-expressing T98G glioma cells." (PMID 40141375, 2025). "Notably, a significant proportion of gliomas were not assessed for MGMT-methylation status, especially amongst IDH1/2-mutant tumors." (PMID 39164213, 2025). "In addition to its relevance in MGMT-silenced GBM, KL-50 may have therapeutic utility in IDH-mutant gliomas, which frequently exhibit MGMT promoter methylation and are prone to acquiring TMZ-induced MMR deficiency 15,38,91." (PMID 41169667, 2025). "In the present study, rADCmin could effectively differentiate MGMT promoter methylation status in the IDH wild-type subgroup (AUC = 0.78), leading us to hypothesize that IDH wild-type gliomas have more significant differences in ADC values due to higher cellular heterogeneity and necrotic tendency." (PMID 40958862, 2025).
glioma (continued). "Additionally, SIGLEC7 was highly expressed in IDH wild-type glioma patients, those without 1p/19q co-deletion, and those without MGMT promoter methylation." (PMID 39211050, 2024). "There were 17 gliomas with MGMT promoter methylation and 16 without." (PMID 39759149, 2024). "Restoring GLS2 expression in T96G glioma cells inhibited cell proliferation, survival, and migration; furthermore, it increased cell sensitivity to alkylating agents like temozolamide (TMZ) and carmustine by downregulating O6-methylguanine-DNA methyltransferase (MGMT)." (PMID 38786726, 2024). "Notably, in contrast to other IDH‐mutant gliomas, where O‐6‐methylguanine‐DNA methyltransferase (MGMT) promoter hypermethylation is a common feature in majority of the cases, PMMRDIA shows the highest frequency of unmethylated MGMT promotor." (PMID 38339779, 2024). "However, the data published by different teams did not contain the molecular typing of glioma, such as MGMT methylation information, so the effect of photodynamic therapy on different grades of glioma needs to be studied in multi-center and large samples." (PMID 38835394, 2024). "Gliomas lacking both the 1p/19q co-deletion and MGMT methylation commonly exhibit TMZ resistance." (PMID 39574472, 2024). "MGMT expression may be epigenetically silenced by promoter hypermethylation in gliomas, however prior clinical testing of this patient’s tumor sample confirmed that the MGMT promoter region was not hypermethylated." (PMID 38287261, 2024). "However, MGMT is not expressed in many gliomas, rendering these hypersensitive to very low (∼10 μM) TMZ concentrations." (PMID 39011394, 2024). "Interestingly, TMZ resistance was found to readily build up in cell culture in the MGMT-negative but not in the MGMT-positive glioma lines upon as few as two 3-day cycles of TMZ treatment." (PMID 39011394, 2024). "Our study found no significant perfusion signal difference in MGMT-non/methylated gliomas." (PMID 39036439, 2024). "Therefore, MGMT methylation in gliomas is a favorable prognostic finding, independent of therapeutic modalities such as the use of alkylating agents." (PMID 37626776, 2023). "This might help explain the unexpected benefit of TMZ reported in a subset of patients whose gliomas tested negative for MGMT promoter methylation." (PMID 37919784, 2023). "However, the role of WEE1 in glioma was also found to be connected to the MGMT status, which was not considered in our analysis." (PMID 37400829, 2023). "In addition, TRIM56 expression was significantly different among glioma subtypes (IDH-wild type vs. IDH-mutant, MGMT promoter methylated vs. MGMT promoter unmethylated, and Chromosome 1p19q codeletion vs. Chromosome 1p19q non-codeletion) in the CGGA_mRNAseq_325 and TCGA databases." (PMID 36870986, 2023). "Statistical analyses indicated moderate overall agreement of FFPE glioma samples and SF MSP semi-quantitative measurements (Fleiss’ Kappa Coefficient = 0.516/0.509; 70.0% agreement) and emphasized their low reliability in the assessment of highly methylated MGMT promoter samples." (PMID 36766464, 2023). "However, BCL2A1 expression did not accurately predict the survival of glioma patients with unmethylated MGMT promoters." (PMID 37889551, 2023). "Additionally, the risk score was significantly increased in samples with the molecular characteristics of IDH-wildtype, chromosome 1p/19q non-codeleted and MGMT promoter unmethylated, which were generally thought to drive the malignant progression of glioma." (PMID 37488496, 2023). "Since MGMT methylation is not predictive in all high-grade gliomas, additional methods that predict tumor response to chemotherapy could help close a gap in clinical decision making." (PMID 36632958, 2023).
glioma (continued). "Furthermore, high ZDHHC15 expression was significantly associated with worse prognosis in patients with IDH1 wild-type and mutant glioma, 1p/19q non-codeletion glioma, MGMT promoter methylated and non-methylated glioma, and primary and recurrent glioma." (PMID 37161425, 2023). "It is compatible with Illumina Novaseq 6000 (JAX SOMASEQ - Clinical test - NIH Genetic Testing Registry GTR - NCBI, 2023) and could be used for the diagnosis of glioma, however, it misses p-TERT DNA sequence alterations, p-MGMT methylation, and important CNVs such as 1p/19q codeletion." (PMID 37908227, 2023). "TMZ resistance has been linked to MGMT promoter methylation status, but recent evidence indicates that MGMT methylation status may not be predictive of TMZ response in all gliomas." (PMID 36632958, 2023). "The glial neoplasm consisted of a population of morphologically heterogeneous, highly proliferating cellular elements with MIB-1 labeling index of 70%, O-6-methylguanine-DNA methyltransferase (MGMT) methylated, and isocitrate dehydrogenase (NADP(+)) 1 (IDH-1) wild type." (PMID 40729189, 2023). "In conclusion, our study demonstrated that novel chemoresistance-associated circWDR62 can be transported via exosomes and that exosomal circWDR62 might function as a miR-370-3p sponge to regulate MGMT expression, promoting the TMZ resistance and malignant development of glioma in vitro and in vivo." (PMID 35817771, 2022). "In contrast, O-6-Methylguanine-DNA methyltransferase (MGMT) is a key enzyme for DNA repair, which functions as removing alkyl groups from guanine residues, thereby counteracting TMZ-induced DNA damage, an important mechanism in the resistance of glioma cells to TMZ treatment." (PMID 36248966, 2022). "demonstrate that glioma cells stimulate normal human astrocyte (NHA) into reactive astrocyte (RAS) in a noncontact manner and the amount of O6‐alkylguanine DNA alkyltransferase (MGMT) mRNA in exosomes released by RAS is significantly higher than that from nonreactive NHA." (PMID 36253096, 2022). "A large subset of gliomas are now defined based on the presence/absence of isocitrate dehydrogenase (IDH) mutation, O6-methylguanine-DNA methyltransferase (MGMT) promoter methylation, and 1p/19q co-deletion, which can help in management and stratification of glioma patients." (PMID 35785190, 2022). "In gliomas, the ITGA5 transcriptional levels increased with more adverse clinicopathological characteristics, namely, greater age at diagnosis, 1p/19q non-codeletion, higher grade, wild-type isocitrate dehydrogenase (IDH) status, unmethylated MGMT status, and mesenchymal subtype." (PMID 35371978, 2022). "In addition, strong expression of Ki-67, partial expression of EGFR and VEGF, and weak expression of MGMT and HIF-1α was oberserved on immunohistochemical staining, These supplementary characteristics will make GSC glioma model a better test platform for glioma." (PMID 36591483, 2022). "Importantly, MGMT‐negative glioma cells uptake exosomes from RAS and gain TMZ resistance by translating exogenous exosomal MGMT mRNA." (PMID 36253096, 2022). "This way, glioma patients may still benefit from alkylating chemotherapy, regardless of their MGMT promotor status." (PMID 35406593, 2022). "Importantly, we showed that disruption to FA pathway function was able to render glioma cells sensitive to temozolomide irrespective of MGMT status/expression levels, demonstrating a potential large scope for such an approach within the clinical setting." (PMID 34036721, 2022). "The results showed that in the TCGA dataset, the risk score was elevated in the IDH wild-type (WT), 1p/19q non-codeletion subtype, MGMT promoter unmethylated subtype, older patients, and high-grade glioma (p < 0.05); we validated these results in the CGGA dataset." (PMID 36035133, 2022). "Hence, an additive effect of combined treatment in MGMT negative canine glial tumour cell lines in vitro was detected." (PMID 34477324, 2021).
glioma (continued). "However, CHI3L2 expression levels of glioma cells were not significantly related to gender, location, TERT promoter mutation status, and MGMT promoter methylated status." (PMID 33937022, 2021). "The presence of methylated CpG islands in the O6-methylguanine-DNA methyltransferase (MGMT) promoter is a molecular marker of better response to DNA alkylating agents, indicating that the methylation status of MGMT promoter is a critical feature to design glioma treatment." (PMID 34168976, 2021). "Considering that RIP2 can induce TMZ resistance in glioma cells, we pretreated the resistant cells (T98G/TR and U87MG/TR) and RIP2‐overexpressing cells (T98G and U87MG) with NF‐κB chemical inhibitors (SC75741, SN50, and JSH‐23) and an MGMT chemical inhibitor (lomeguatrib), respectively." (PMID 33460245, 2021). "However, the significance of genetic variations of MGMT in glioma carcinogenesis has not been fully elucidated." (PMID 34544433, 2021). "Gliomas with MGMT-non-pM are striking resistant to chemotherapy or targeted therapy." (PMID 34412650, 2021). "In addition, we observed that unfavorable molecular features in glioma such as IDH wild-type, 1p/19q non-codeletion, and MGMT promoter unmethylation were all associated with a higher HRLscore." (PMID 34869006, 2021). "Besides, LYN was enriched in CL and ME subtype of gliomas, which indicated worse survival, and LYN was associated with 1p19q non-codeletion and unmethylated MGMT promoter, both of which predicted worse survival in glioma patients." (PMID 35186945, 2021). "Second, despite the IDH1R132H mutation being the most influential genetic factor for postoperative oncological outcomes of gliomas, information concerning other potential factors such as the chromosomal 1p/19q codeletion, IDH2 or MGMT mutation, and ATRX mutation was not considered." (PMID 34389754, 2021). "High CHI3L2 expression indicates a poor prognosis for glioma patients, regardless of whether the MGMT promoter is methylated or has received adjuvant therapy." (PMID 33937022, 2021). "Moreover, PDIA5 expression was upregulated in the MGMT promoter non-methylated samples of pan-glioma patients." (PMID 33664747, 2021). "Furthermore, we found regardless of whether patients with glioma have methylation of the MGMT promoter or have received adjuvant therapy, high CHI3L2 indicates a poor prognosis for glioma." (PMID 33937022, 2021). "However, recent clinical practice showed that TMZ was less effective for prolonging patient survival in a considerable number of high grades glioma patients with high MGMT expression without promoter region methylation." (PMID 33621205, 2021). "Additionally, ARL score was significantly higher in IDH1 wildtype, 1p19q non-codeleted, and MGMT unmethylated gliomas (p < 0.05)." (PMID 34211979, 2021). "Thus, MGMT methylation is distinct from the invasiveness of the glioma and was not related to alterations of FA or MD." (PMID 33777772, 2021). "All of them as well as the human glioma cell lines had no detectable level of MGMT protein." (PMID 34477324, 2021). "Repair mechanisms that lead to resistance and that are common in glioma cells include DNA mismatch repair, homologous recombination (HR), non-homologous end joining (NHEJ) as well as the removal of guanine methylation by O6-methylguanine-DNA methyltransferase (MGMT)." (PMID 33809019, 2021). "Furthermore, a better prognosis for survival in glioma cases was indicated for IDH gene status irrespective of positive or negative with MGMT promoter methylation." (PMID 33552543, 2020). "The delivery of this mRNA to MGMT-negative glioma cells may confer the resistance to temozolomide, through the repression of apoptosis." (PMID 33569385, 2020). "This has led to a consensus in North America and Europe that TMZ could be excluded as a standard treatment for unmethylated MGMT glioma patients." (PMID 33392065, 2020).
glioma (continued). "Interestingly, Qiu and colleagues demonstrated that glioma-stem like cells derived from the naturally MGMT-negative cell line U251-MG become MGMT-positive on the protein level, which contributes to their TMZ resistance." (PMID 33318498, 2020). "Furthermore, using quantitative and non-quantitatve methods we have observed methylation of the MGMT gene promoter, a hallmark of IDH1 mutant gliomas." (PMID 32946483, 2020). "However, to the best of our knowledge, there is no previous report regarding building a pipeline for both glioma tumor segmentation and MGMT methylation status prediction in an end-to-end manner." (PMID 33029531, 2020). "Despite many investigations pointing to O6-methylguanine-DNA-methyltransferase (MGMT) as being responsible for tumor chemo-resistance, its expression does not predict an accurate response in most gliomas, suggesting that MGMT is not the only determinant of response to treatment." (PMID 33335215, 2020). "Also, studies investigating ADC histogram profiling regarding MGMT promotor methylation status in low-grade glioma are completely lacking." (PMID 32158691, 2020). "Our studies detected five proteins that interacted with Fstl1 in glioma using Co-IP and pulldown experiments, i.e., DIP2A, CD14, BMP4, ActR-IIB, and follistatin, and the mRNA levels of MGMT were only increased in GBM cells transfected with DIP2A-specific siRNA (siDIP2A)." (PMID 30542120, 2019). "In search of novel clinical and molecular prognostic factors of this rare adult glioma subtype, we analyzed our institutional series of sporadic, intracranial, adult PAs WHO grade I with particular emphasis on the prognostic significance of MGMT promoter methylation status." (PMID 31362435, 2019). "Furthermore, we show that down-regulation of ALDH3A1 increases TMZ sensitivity and reduces stemness features in glioma cells in vitro independent of the MGMT promoter methylation status." (PMID 29854309, 2018). "Thus PAM-OBG can ablate MGMT activity and create acrolein-DNA adducts in glioma cells, but not in tissues with low levels of MAOB." (PMID 29844863, 2018). "In the present study, we detected increased global hypomethylation (Alu) and regional hypermethylation (MGMT, RASSF1A, P16) in serum cell-free DNA of glioma patients compared to healthy controls, and demonstrate that both Alu and MGMT may have good diagnostic value." (PMID 29100349, 2017). "However, the expression of P2RY12 is not an independent prognosticator in gliomas; when strong prognostic factors as IDH mutational status or methylation status of MGMT are taken into consideration, no additional effects of the expression are found." (PMID 28073370, 2017). "DNA repair protein O6-methylguanine-DNA methytransferase (MGMT) plays a key role in TMZ resistance; transcription factor specificity protein 1 (SP1), a regulator of DNA mismatch repair (MMR) key protein MSH6, has been reported to be up-regulated in TMZ-resistant glioma cell lines." (PMID 28831025, 2017). "The prognostic information of rs1625649 in MGMT methylated gliomas was, however, not provided." (PMID 29036186, 2017). "However, MGMT overexpression is a main reason for glioma drug resistance in clinical cases, and collagen, not hyaluronic acid, is the main ECM component in glioma tissues." (PMID 27486877, 2016). "Importantly, we observed that TERT promoter mutations particularly C228T and long telomere length significantly impacted radiotherapy outcome in glioma patients, which appears independent of WHO grade, KPS score, IDH1 mutations and MGMT methylation." (PMID 26556853, 2016).